INS (insulin)
Diseases named in the same sentence as INS in open-access papers (continued):
Sharing a sentence is not in itself a finding about the gene and the disease.
Hyperglycemia (continued). "In most cases of T2DM, insulin resistance is the initial pathological mechanism, with hyperglycemia developing when β cells fail to compensate with insulin hypersecretion." (PMID 33250773, 2020). "Maternal hyperglycemia affects the fetus’s hormonal response and its insulin secretion, which is crucial for fetal organogenesis and growth." (PMID 32933073, 2020). "Pan-PI3K inhibitors induce transient hyperglycemia and, consequently, a compensatory increase in insulin production and secretion that can reactivate PI3K signaling in tumor cells." (PMID 32630618, 2020). "Type II ketosis mainly occurs within 1 to 2 weeks postpartum, is induced by lipid deposition and gluconeogenesis reduction, and has high serum ketone, NEFA, and INS concentrations and slight hyperglycemia (or average Glu level)." (PMID 32054179, 2020). "Apart from exercise and nutrition, pharmacological interventions are applied to alleviate hyperglycemia and insulin resistance." (PMID 33171690, 2020). "We discuss the use of antidiabetic drugs in a wide range of cancer therapy and cancer therapeutics in the development of hyperglycemia, especially antineoplastic drugs which often induce hyperglycemia by targeting insulin/IGF-1 signaling." (PMID 32498358, 2020). "The type, dose, and timing of insulin are determined by the timing and severity of hyperglycemia, and treatment is customized for each patient." (PMID 33371325, 2020). "The function is very similar to the other two DIYCL systems, as an algorithm analyzes the data provided by the insulin pump and CGM and makes decisions as to how to deliver insulin in the case of hyperglycemia." (PMID 33332410, 2020). "To understand the source of increased insulin production in obese SM/J mice, we examined islet morphology during the resolution of hyperglycemia." (PMID 33113267, 2020). "The theoretical prediction of [Na] increase by 1.6 mmol/L per 5.6 mmol/L decrease in [Glu] in most clinical settings, except in extreme hyperglycemia or profound hypervolemia, was supported by studies of hyperglycemia in CKD stage 5 treated only with insulin." (PMID 32984372, 2020). "They received standard hypoglycemic therapy with oral anti-hyperglycemia agent and/or insulin subcutaneous injection." (PMID 32489451, 2020). "Such hyperglycaemia requires either transient treatment with insulin in about half of cases, or permanent insulin treatment." (PMID 33102403, 2020). "Several pharmacotherapies including statins, some angiotensin-converting enzyme (ACE) inhibitors, perhexiline, and insulin (in the presence of severe hyperglycemia) ameliorate NO• resistance, while sGC activators primarily circumvent the problem." (PMID 32508651, 2020). "On the other hand, in T2DM it has been considered that defects in insulin action induce hyperglycemia." (PMID 33339276, 2020). "After processing input data of CGM, insulin dosed, and self-reported meals, the group developed three classifiers to predict hypoglycemic events (<70 mg/dL), hyperglycemia (>180 mg/dL), and within target range (70–180 mg/dL)." (PMID 32517068, 2020). "Hyperglycemia with insulin insensitivity in the first few postnatal weeks of life is a common complication in extremely preterm infants." (PMID 33004691, 2020). "Previously, we suggested that amylase has possible regulatory effects only on postprandial hyperglycemia and on insulin/glucagon release, as in previous studies by our lab, we showed that the mode of amylase infusion did not affect basal glucose levels." (PMID 33294459, 2020). "At times, patients with mild hyperglycaemia, ranging from 150 to 200 mg/dL, received anywhere from 0 to 16 units of boluses of short acting insulin." (PMID 32612144, 2020). "Implantation of islet-seeded biomaterial into either STZ-induced or NOD diabetic mice resulted in significant reduction of hyperglycemia coupled with marked increase in insulin levels." (PMID 32152396, 2020).
Hyperglycemia (continued). "Short-term symptoms are hyperglycaemia or hypoglycaemia, the latter being the result of insulin treatment." (PMID 32244496, 2020). "Clinicians of the panel believe that safe management of hyperglycemia requires only the use of insulin." (PMID 33008391, 2020). "Insulin can be administered throughout the day in divided doses or be given as a single daily dose depending on the timing of hyperglycemia." (PMID 33371325, 2020). "Nonetheless, STZ as administered here reduced plasma insulin substantially (by 82–84%), via efficacious reduction in pancreatic β cell mass, and induced hyperglycemia, which are key hallmarks of type 1 diabetes." (PMID 33042003, 2020). "Modern pharmacological studies have shown that ginsenoside can repair islet β cells, promote insulin release, and can inhibit alloxan and improve hyperglycemia." (PMID 33062014, 2020). "It has been reported that β cell mass was reduced by approximately 29% in CP patients; and that reductions in insulin secretion and hyperglycemia occur in CP patients with β cell mass < 40% of the normal." (PMID 33250773, 2020). "Increased circulating glucose and insulin together with decreased insulin sensitivity contribute to hyperglycemia and hyperinsulinemia, while excessive circulating lipids resulting from decreased fatty acid oxidation lead to hyperlipidemia." (PMID 33088334, 2020). "It is a metabolic disorder characterized by the presence of hyperglycaemia attributable to a reduction in insulin secretion or insulin action or both." (PMID 32550226, 2020). "We sought to examine if changes in β‐cell insulin secretion and content corresponded with the resolution of hyperglycemia and expanded β‐cell mass we observe." (PMID 33113267, 2020). "Elevated postprandial blood glucose is a major characteristic of GC-induced hyperglycemia, and treatment with multiple insulin injections is often necessary for glycemic control." (PMID 32381085, 2020). "As expected, Ins1−/−;Ins2f/f mice injected with AAV8 Ins1-Cre developed hyperglycemia and had reduced glucose-stimulated insulin secretion." (PMID 32601405, 2020). "On the other hand, insulin protein levels are already increased 30 min after exposure of rodent and human islets to hyperglycaemia." (PMID 32894308, 2020). "This blocks the ability of insulin to increase tissue uptake of glucose in a normal manner and leads to hyperglycemia and decreased glucose utilization." (PMID 33167495, 2020). "DM is a chronic disease that is recognized by hyperglycemia (HG) resulting from impaired insulin secretion, inappropriate insulin action, or both." (PMID 32660119, 2020). "In very preterm infants, the incidence of hyperglycemia is high, reaching 20% to 86%, due to immature insulin production and insulin resistance." (PMID 33306685, 2020). "Mice in the DC group showed hyperglycemia, lipid metabolism disorders, and high serum insulin levels, indicating that the diabetic mice model was successfully created." (PMID 33061888, 2020). "In people with type 1 diabetes, the incidence of infection often results in hyperglycemia and frequent insulin injection." (PMID 32784179, 2020). "Our results support a model in which skeletal muscle activity induces BDNF secretion, enhancing insulin secretion and glucose removal from the blood during hyperglycemia." (PMID 32327658, 2020). "The diabetic strain of rats had accelerated development of hyperglycemia and suppressed insulin secretion from β-cells of pancreatic islets, probably due to increased apoptosis and decreased mass of β-cells during the subjective day." (PMID 32751870, 2020). "They showed the reduction of insulin and leptin sensitivity, alteration of neuropeptide expression, hyperglycemia and compromised β-cell function." (PMID 32948162, 2020). "Impaired glucose-induced insulin release and hyperglycemia were found in rats under anesthesia with sevoflurane or isoflurane." (PMID 32240260, 2020).
Hyperglycemia (continued). "The failure of experimental alteration in insulin signalling to alter steady state glucose raises two distinct possibilities about fasting hyperglycaemia in T2D." (PMID 33365205, 2020). "Since insulin deficiency is the cause of hyperglycemia in T1DM, the most common treatment for this form of the disease is injection of insulin." (PMID 33396883, 2020). "Taken together, the islet-seeded biomaterial can reduce hyperglycemia by restoring insulin levels in a glucose-responsive manner in both STZ-induced and autoimmune-driven NOD diabetic mouse models." (PMID 32152396, 2020). "Our findings indicated that 2 months of fructose intake, triggered metabolic derangements in spontaneously hypercholesterolemic ApoE-KO mice, mimicking MetS characterized by dyslipidemia, high insulin levels and hyperglycemia." (PMID 33154969, 2020). "In women experiencing postprandial hyperglycemia following specific meals only, rapid-acting insulin should be considered prior to the meal." (PMID 33371325, 2020). "Omitting insulin altogether, well in advance of exercise, promotes excessive hyperglycaemia and ketone production." (PMID 32533229, 2020). "Because of its central role in glucose homeostasis, insulin administration is the standard therapy for hyperglycemia in diabetic patients." (PMID 32017705, 2020). "HFD-fed rats treated with an IL-1 receptor antagonist show improvements in hyperglycemia, islet insulin biosynthesis, insulin sensitivity, and decreased macrophage islet infiltration." (PMID 33457426, 2020). "To answer this question, we conducted an OGTT (both hyperglycemia and hyperinsulinemia) to study the impacts of nutritional status and hormone (insulin) on serum Fetuin-B in vivo." (PMID 33061822, 2020). "During hyperglycaemia, the sustained demand for insulin results in programmed cell death of β-cells." (PMID 31396860, 2020). "This is likely due to prolonged hyperglycemia and hyperosmolarity, chronic low insulin signaling, and/or dyslipidemia." (PMID 32326182, 2020). "Resveratrol has an important role in controlling hyperglycemia and plasma insulin levels and demonstrates increased expression of PPAR-γ and FALDH in rat adipose tissue." (PMID 33287318, 2020). "Overall, boluses of short acting insulin were utilized more commonly than infusions of short-acting insulin for controlling hyperglycaemia." (PMID 32612144, 2020). "In β-cells, IRE1 also has roles in enhancing insulin biosynthesis in response to acute hyperglycemia and degrading insulin mRNA during prolonged ER stress." (PMID 33457426, 2020). "Multiple insulin injections is often necessary for glycemic control of glucocorticoid (GC)-induced hyperglycemia." (PMID 32381085, 2020). "In fact, despite fasting normoglycemia, the HFD-treated rats presented fed hyperglycemia and hyperinsulinemia, with glucose intolerance and reduced insulin sensitivity." (PMID 32218109, 2020). "Sustained hyperglycemia is indeed one of the factors that impairs the insulin-mediated regulation of glucose homeostasis and glycogen synthesis in the muscle and liver cells." (PMID 32751097, 2020). "Insulin deprivation and/or sustained hyperglycaemia can impair mitochondrial function, promote mitophagy, lower ATP provision and increase reactive oxygen species production in muscle, heart, kidney and brain." (PMID 32533229, 2020). "Patients with T2DM are unable to control the disease by lifestyle changes alone, and require drugs and insulin for reducing the hyperglycemia." (PMID 32847055, 2020). "Withholding early-PN has shown to reduce the degree of hyperglycemia, to lower the insulin requirements to prevent hyperglycemia, and to lower the insulin/glucagon ratio." (PMID 32867803, 2020). "As they resolve hyperglycemia, obese SM/J mice dramatically increase circulating and pancreatic insulin levels while improving insulin sensitivity." (PMID 33113267, 2020).
Hyperglycemia (continued). "With OLAN treatment, in addition to its induction of INPP5D, the suppression of AMY2B and GNAI1 are predicted to increase hyperglycemia and decrease insulin sensitivity." (PMID 33302598, 2020). "Thirteen children (9 in Plasma-Lyte-A and 4 in 0.9% saline) required increment of insulin infusion for persisting hyperglycemia." (PMID 31898531, 2020). "Automated insulin delivery and CL systems were shown to provide a significant improvement in HbA1c values, a significant reduction in hypoglycemia and hyperglycemia or increased TIR, and an improvement in the quality of life and sleep." (PMID 33332410, 2020). "The disease is characterized by increased blood glucose levels (hyperglycemia) as a result of impaired insulin secretion due to pancreatic beta (β)-cell dysfunction and insulin resistance." (PMID 32664305, 2020). "In parallel with protection against oxidative stress, NAC restored hyperglycemia and improved glucose tolerance and insulin sensitivity in DEHP-exposed mice." (PMID 32802189, 2020). "Dietary intake of genistein significantly improved hyperglycemia, glucose tolerance, and blood insulin levels in streptozotocin-induced diabetic mice, concomitant with improved islet β-cell proliferation, survival, and mass." (PMID 33255206, 2020). "In individuals with NDM, impaired insulin secretion results in a low birth weight and hyperglycemia diagnosed before the age of 6 months." (PMID 32027066, 2020). "Water intake from hyperglycemia led to hyponatremia after correction with insulin of approximately one-third of the hyperglycemic episodes in dialysis patients." (PMID 32984372, 2020). "For example, a single injection of STZ to rats at a dose of > 60 mg/kg b.m. can lead to drastic destruction of β cells; thus, insulin secretion declines resulting in significant chronic hyperglycaemia." (PMID 30826908, 2020). "Due to the overproduction of insulin, β cell functions will be impaired and will ultimately lead to chronic postprandial hyperglycaemia and fasting hyperglycaemia." (PMID 32377517, 2020). "The critical point of this finding is that this impairment in microvascular function paralleled decrements in insulin sensitivity and postprandial hyperglycemia." (PMID 33050169, 2020). "Keeping blood glucose within range is an extraordinary challenge, as GCs induce a pronounced postprandial hyperglycemia due to increased glucose intolerance and insulin resistance." (PMID 33348743, 2020). "Luteolin, a flavonoid, was shown to reduce hyperglycaemia by raising insulin secretion in a diabetic animal model." (PMID 33299532, 2020). "Inhaled insulin shows a similar physiologic response to subcutaneous insulin, with a faster onset of action, making it suitable for post-prandial hyperglycemia." (PMID 32850233, 2020). "GLP-1, a hormone secreted by the small intestine after a meal, has been observed to restore insulin sensitivity and attenuate hyperglycemia in humans." (PMID 33343375, 2020). "In a study with ob/ob mice, ghrelin deletion decreased hyperglycemia and improved glucose-induced insulin secretion, thus improving insulin sensitivity in peripheral tissues compared with ob/ob controls." (PMID 32121443, 2020). "For example, in patients who develop steroid-induced hyperglycemia, adding insulin treatment or adjusting its dose is a common and effective treatment and the same applies to patients with hypertension by adjusting BP medications if needed." (PMID 34901264, 2020). "Its down-regulation has been shown to induce hyperglycemia, impaired insulin secretion, glucose intolerance and hyperlipidemia." (PMID 33020388, 2020). "As expected, the hyperglycemia led to very high insulin levels compared with control mice (day 0); the levels decreased when the hyperglycemia was ameliorated." (PMID 31743040, 2020). "Liver-specific knockdown of Zbtb16 relieved hyperglycemia in db/db mice and led to decreased insulin levels, improved glucose and pyruvate tolerance, and insulin sensitivity." (PMID 33061941, 2020).
Hyperglycemia (continued). "Progression of the disease makes insulin secretion unable to maintain glucose homeostasis, producing hyperglycaemia." (PMID 32872570, 2020). "The STAR Upper Limit Controlled approach mitigated hyperglycaemia and had lower insulin and significantly lower nutrition administration rates." (PMID 32349750, 2020). "We have highlighted many experiments to overcome hyperglycemia such as differentiating MSCs into IPCs (insulin-producing cells), mitigating insulin resistance, conversion of alpha cells to beta cells and remodeling pancreatic regeneration." (PMID 32384763, 2020). "IPGGT studies on streptozocin (STZ)-induced diabetic mice treated with the insulin gene, delivered intrapancreatically by recombinant Ad (rAD) vector, corrected hyperglycemia and glucose tolerance." (PMID 32489555, 2020). "Insufficient levels of insulin along with excess glucagon production lead to hyperglycemia and ketoacidosis." (PMID 32566684, 2020). "Normally, a small ratio of insulin-to-carbohydrate signifies that the patient consumed more carbohydrates and injected less insulin, which normally derives the blood glucose dynamics into the hyperglycemia region." (PMID 32784179, 2020). "The decline of insulin activity and the hyperglycemia/hypoglycemia greatly affect the body in many ways." (PMID 33218062, 2020). "In women with GDM suppressed endogenous glucose production and more pronounced decrease in peripheral insulin sensitivity contribute to fasting hyperglycemia." (PMID 32574162, 2020). "For example, lncRNA H19 inhibition in vivo induced hyperglycemia and impaired glucose, insulin, and pyruvate tolerance in liver tissue." (PMID 32765426, 2020). "SeNPs administration successfully reduced the hyperglycemia, raised the levels of insulin in both the pancreas and the plasma and restored the damaged pancreatic tissue." (PMID 32509990, 2020). "We avoided the delay model also because in the perfused pancreas the insulin secretion response to a square wave of hyperglycemia is incompatible with a first-order delay, as it shows a slow onset but a fast offset." (PMID 33324238, 2020). "But, in an insulin-resistant state, a cessation in the adjustment of this metabolism ensues hyperglycemia and dyslipidemia, which further aggravates the development of hepatic steatosis." (PMID 32211252, 2020). "Even mild hypokalemia, when induced by thiazide diuretics, can lead to hyperglycemia through dysfunction of the potassium pump that regulates insulin secretion." (PMID 32423140, 2020). "As a complex and progressive metabolic disease, T2D is characterized by chronic hyperglycemia resulting from defects in insulin secretion and action due to β-cell dysfunction and insulin resistance in target organs." (PMID 33043040, 2020). "Assessing insulin sensitivity is difficult, with varying definitions, and the focus with respect to glucose homeostasis is usually hyperglycaemia." (PMID 33013688, 2020). "In patients with type 1 diabetes with COVID-19 and hyperglycaemia, it is important to monitor the blood glucose and ketone levels, maintain hydration and continue insulin therapy." (PMID 32405783, 2020). "Taking into account the role of hyperglycemia as a marker of stress during and after cardiac surgery, it is feasible that insulin administration in this setting is blunting other necessary physiologic pathways leading to worse clinical outcomes." (PMID 33118731, 2020). "The panel recommended the use of insulin-based therapy in T2DM patients with symptoms of hyperglycemia." (PMID 32489427, 2020). "The gluconeogenesis is inhibited by insulin in the postprandial condition to attenuate the meal-induced hyperglycemia." (PMID 32440681, 2020). "This in turn creates a strong incentive to withhold or reduce insulin, leading to chronic hyperglycaemia." (PMID 32704558, 2020). "Specifically, increases in circulating DPP4 would lead to a decrease in GLP-1, leading to reduced insulin and increased glucagon secretion, resulting in hyperglycemia." (PMID 31911667, 2020).